LINC00479 (long independently transcribed non-coding RNA 479)
Synonyms: C21orf129; PRED76; FLJ32835
Gene: Long non-coding RNA gene on chromosome 21 (41,711,461 to 41,715,775, reverse strand). Ensembl gene ENSG00000236384.
Diseases named in the same sentence as LINC00479 in open-access papers:
LINC00479 is named in the same sentence as 1 disease in open-access papers, as found by Europe PMC text mining. Sharing a sentence is not in itself a finding about the gene and the disease. The quoted sentences say what the papers report.
tumor (1 paper, 2024). "In a glioblastoma tumor xenograft mouse model, the high expression of LINC00479 was found to correlate well with the rapid growth of the tumor." (PMID 39403602, 2024).